SNORD49A (small nucleolar RNA, C/D box 49A)
Synonyms: U49; U49A; RNU49
Gene: Small nucleolar RNA gene on chromosome 17 (16,440,036 to 16,440,106, forward strand). Ensembl gene ENSG00000277370.
Gene Ontology:
Biological process: RNA processing
Cellular component: nucleolus
Homologues: Orthologues: chimpanzee SNORD49A (100% identical), macaque SNORD49A (99% identical), pig SNORD49A (92% identical), mouse Snord49a (86% identical), rabbit SNORD49A (85% identical), rat Snord49a (80% identical). Paralogues in human: SNORD49B (80% identical).
Diseases named in the same sentence as SNORD49A in open-access papers:
SNORD49A is named in the same sentence as 1 disease in open-access papers, as found by Europe PMC text mining. Sharing a sentence is not in itself a finding about the gene and the disease.
SNORD49A shares sentences with these, for which no sentence is quoted: leukemia (1 paper).